ZNF705D (zinc finger protein 705D)
Description:
May be involved in transcriptional regulation.
Synonyms: ZNF705C
Tractability: No criterion of Open Targets' tractability assessment is met for any kind of drug.
Gene: Protein-coding gene on chromosome 8 (12,089,338 to 12,115,516, forward strand). Ensembl gene ENSG00000215343.
Subcellular location: Nucleus
Pathways (Reactome):
Gene expression (Transcription): Generic Transcription Pathway
Gene Ontology:
Molecular function: protein binding; DNA-binding transcription factor activity, RNA polymerase II-specific; RNA polymerase II transcription regulatory region sequence-specific DNA binding; sequence-specific double-stranded DNA binding
Biological process: regulation of transcription by RNA polymerase II; regulation of DNA-templated transcription
Cellular component: nucleus
Genetic constraint (gnomAD): Loss-of-function variants: 0 observed, 0.64 expected, observed/expected ratio (o/e) 0, 90% interval 0 to 1.81. That is too few expected variants to judge how well the gene tolerates losing a copy. Missense variants: 4 observed, 19.02 expected, observed/expected ratio (o/e) 0.21, 90% interval 0.1 to 0.48. Synonymous variants: 0 observed, 5.41 expected, observed/expected ratio (o/e) 0, 90% interval 0 to 0.55.
Homologues: Orthologues: mouse Zfp78 (35% identical), Drosophila melanogaster CG3281 (23% identical), Drosophila melanogaster CG2712 (21% identical), Drosophila melanogaster Phs (19% identical). Paralogues in human: ZNF705B (99% identical), ZNF705A (96% identical), ZNF705G (93% identical), ZNF596 (53% identical), ZFP90 (42% identical), ZNF555 (37% identical), ZNF266 (37% identical), ZNF77 (36% identical), ZFP69B (36% identical), ZNF805 (36% identical), ZNF599 (36% identical), ZNF264 (35% identical), and 50 more.
Diseases named in the same sentence as ZNF705D in open-access papers:
ZNF705D is named in the same sentence as 1 disease in open-access papers, as found by Europe PMC text mining. Sharing a sentence is not in itself a finding about the gene and the disease. The quoted sentences say what the papers report.
cancer (1 paper, 2021). A tumor composed of atypical neoplastic, often pleomorphic cells that invade other tissues. "Furthermore, the roles of KCNA10 and ZNF705D in the pathogenesis of cancer, including OSCC, have not been investigated, implying the novel insights gained from this study and new avenues for the diagnosis of and new treatment strategies for OSCC." (PMID 34051764, 2021).